SPRN (shadow of prion protein)
Diseases named in the same sentence as SPRN in open-access papers (continued):
Sharing a sentence is not in itself a finding about the gene and the disease.
scrapie (5 papers, 2009 to 2024). A fatal disease of the nervous system in sheep and goats, characterized by pruritus, debility, and locomotor incoordination. "Susceptibility to scrapie in goats is related to insertion polymorphisms in the 3′ untranslated region (UTR) of the caprine SPRN gene." (PMID 39765621, 2024). "Here, we investigated the genotype and allele frequencies of SPRN polymorphisms in 213 Korean native black goats and compared these polymorphisms with those previously reported for scrapie-affected animals." (PMID 31649311, 2019). "Furthermore, a previous study reported that an insertion/deletion polymorphism in the caprine SPRN gene located on the 3′ UTR was associated with susceptibility to scrapie." (PMID 35632724, 2022). "In addition, insertion/deletion polymorphisms in the SPRN gene are associated with vulnerability to scrapie-affected goats and atypical BSE-affected cattle." (PMID 35632724, 2022). "In addition, we evaluated the SPRN genetic type of Korean native black goats, which showed significantly different distributions of a scrapie-related indel polymorphism compared to Italian goats." (PMID 31649311, 2019). "In addition, we compared the genetic distribution of an insertion polymorphism of the SPRN gene in healthy Korean native black goats with that of scrapie-affected goats from previous studies." (PMID 31649311, 2019). "Previous studies have reported that polymorphisms of the shadow of prion protein gene (SPRN) were associated with susceptibility to CJD, scrapie and BSE." (PMID 32943703, 2020). "In addition, genetic susceptibility of the SPRN gene has been reported in variant Creutzfeldt–Jakob disease (CJD), bovine spongiform encephalopathy (BSE) and scrapie." (PMID 31649311, 2019). "Further studies on the transmission genetics of the SPRN indel alleles and the SPRN+PRNP genotypes of scrapie-challenged animals may be enlightening." (PMID 19657386, 2009). "Since the SPRN gene is located on a different chromosome from the PRNP gene, previous association studies for scrapie susceptibility of the SPRN gene were clearly not the result of an LD block with the PRNP gene." (PMID 31649311, 2019).
sporadic CJD (2 papers, 2009 to 2011). "Two UK patients heterozygous for an SPRN frameshift allele were found in a sample of 107 vCJD cases, and a signal peptide sequence missense polymorphism was overrepresented in cases of sporadic CJD." (PMID 22114562, 2011). "In this vein, the human SPRN polymorphism T7M is now reported to be associated with sporadic CJD with a p value of 0.009." (PMID 19657386, 2009). "Perhaps a similar effect may explain how a human SPRN signal peptide polymorphism can alter some aspect of the pathogenesis of sporadic CJD." (PMID 19657386, 2009).
Alzheimer disease (1 paper, 2024). A progressive, neurodegenerative disease characterized by loss of function and death of nerve cells in several areas of the brain leading to loss of cognitive function such as memory and language. "SPRN is a protein with properties similar to those of PrPc, so it is presumed that it may also take part in the development of neurodegenerative diseases in humans, such as Alzheimer’s disease." (PMID 38156998, 2024).
autism (1 paper, 2016). Persistent deficits in social interaction and communication and interaction as well as a markedly restricted repertoire of activity and interest as well as repetitive patterns of behavior. "In addition, there is a report of a patient with autism, ID and microcephaly who showed duplication with a size of 170 Kb containing PAOX, MTG1 and SPRN genes." (PMID 28357200, 2016).
bladder cancer (1 paper, 2022). "Shadow of prion protein (SPRN) is the one which is accurately reported that the SPRN appears exclusively in leiomyoma in contrast to normal samples, and its overexpression can increase the migratory ability of bladder cancer cells." (PMID 36100894, 2022).
neuroblastoma (1 paper, 2009). Neuroblastoma (NB) is the most common solid, extracranial childhood tumor. "Sheep V71, A71, Δ67–70 and 67(Ala)6Gly73 SPRN alleles encoded proteins with similar stability and posttranslational processing in transfected neuroblastoma cells." (PMID 19657386, 2009).
Stroke (1 paper, 2022). Sudden impairment of blood flow to a part of the brain due to occlusion or rupture of an artery to the brain. "Moreover, CBX7 (target of miR-4446), SPRN and STK35 (targets of miR-6721-5p) have also been studied in stroke models." (PMID 35328807, 2022).
variant Creutzfeldt-Jakob disease (1 paper, 2021). A form of Creutzfeldt-Jakob disease that is most commonly contracted after consuming meat from an animal suffering from bovine spongiform encephalopathy. "In variant Creutzfeldt-Jakob disease (vCJD), the insertion G allele at codon 46 of the human SPRN gene induces a frameshift of this gene and it shows a significantly different distribution between the healthy controls and vCJD patients." (PMID 34573540, 2021).
tumor (2 papers, 2022 to 2023). "CASKIN2, TLE2, USP20, SPRN, ARSG, MIR106B, and MIR98 were considered to be substantially expressed in the low-risk group, suggesting that these genes may be PAAD tumor suppressor genes." (PMID 35077391, 2022). "As for SPRN, its function in the context of PDAC or tumor immunity has not been reported, and further research is needed." (PMID 37605192, 2023).
infection (1 paper, 2011). The state of being infected such as from the introduction of a foreign agent such as serum, vaccine, antigenic substance or organism. "Additionally, wheel running enhanced expression of shadow of a prion protein (SPRN), a gene that encodes for the protein Sho that has neuroprotective-like effects against infection with a prion." (PMID 21857943, 2011).
SPRN also shares sentences with these, for which no sentence is quoted: diabetic retinopathy (1 paper); leiomyoma (1); microcephaly (1); neurodegenerative disease (1).